KRAS (KRas proto-oncogene, GTPase)
Diseases named in the same sentence as KRAS in open-access papers (continued):
Sharing a sentence is not in itself a finding about the gene and the disease.
cholangiocarcinoma (continued). "ARID1A is mutated in 7–36% of cholangiocarcinoma (CC), where it frequently co-occurs with KRAS mutations." (PMID 38275587, 2023). "The rate of KRAS mutation in patients with cholangiocarcinoma may range between 7% and 49%." (PMID 36139531, 2022). "Perihilar cholangiocarcinoma (pCCA; Klatskin tumors), originating at the confluence of the right and left hepatic ducts, more frequently harbors KRAS alterations and ERBB2 (HER2) amplification." (PMID 41535645, 2026). "Although rare (estimated in ~0.2% of all solid tumors) NRG1 fusions have been identified in several GI malignancies, including pancreatic ductal adenocarcinoma (~0.5%) (particularly in KRAS wild-type tumors), cholangiocarcinoma (~0.5%), and CRC (~0.1%)." (PMID 41153346, 2025). "This pilot experiment documented synergy of the inhibitors in two KRAS mutated cells with a completely differing NSCLC and cholangiocarcinoma cellular background." (PMID 38023987, 2023). "We next performed a gene set enrichment analysis (GSEA) and found that, compared with SD-type ICC organoids, LD-type organoids exhibited significant enrichment of ‘cholangiocarcinoma class 2’, ‘KRAS dependency, ‘TGFβ-up gene, and ‘ERBB-up gene’ signatures." (PMID 36646721, 2023). "FGFR2 GAs, which are mostly fusions, are found in 10-15% of intrahepatic cholangiocarcinoma’s, compared to 4.4% in our KRAS wild-type PDA cohort." (PMID 37404765, 2023). "Here, the authors analyse KRAS wildtype mPDAC tumours using genomics and transcriptomics and find molecular similarities with cholangiocarcinomas." (PMID 36209277, 2022). "We again observed a distinct cluster (Cluster 1) containing the majority of KRAS wildtype mPDAC (six of eight (75%); p = 3.0e–6) and cholangiocarcinoma (15/25 (60%); p = 6.4e–4) samples." (PMID 36209277, 2022). "Similar to KRAS wildtype mPDAC, amplification of chr1q was observed in approximately 20% of cholangiocarcinoma tumors." (PMID 36209277, 2022). "In cholangiocarcinoma treatment with cyclopamine and MEK inhibitor U0126 showed an additive effect, especially in cells with KRAS mutation." (PMID 25503972, 2014). "Furthermore, the co-occurrence of activating KRAS mutations and ARID1A deletions has been shown to synergistically accelerate cholangiocarcinoma development from cholangiocytes, especially under conditions of liver inflammation." (PMID 41008893, 2025). "To explore the mechanism that mediates the antitumor effect of BI-2493 and BI-2865, we selected the control HEK293T cell line and the KRAS WT–amplified cancer cell lines SNU-245 (cholangiocarcinoma, CN = 28.1), MKN1 (gastric, CN = 12.7), and DMS 53 (NSCLC, CN = 9.6)." (PMID 39711431, 2025).
cholangiocarcinoma (continued). "From a clinical perspective, immediate implications regarding the molecular similarity shared between KRAS wildtype mPDAC and cholangiocarcinoma are limited, as both diseases often receive platinum-based first-line treatment regimens (containing oxaliplatin and cisplatin, respectively)." (PMID 36209277, 2022). "Moreover, using an independent cohort of metastatic cholangiocarcinoma and mPDAC from the Hartwig study, we validated our findings of the transcriptional similarity between cholangiocarcinoma and, specifically, KRAS wildtype mPDAC tumors." (PMID 36209277, 2022). "To validate our finding of distinct mRNA-based similarities between cholangiocarcinoma and KRAS wildtype mPDAC, we leveraged RNAseq data for cholangiocarcinoma (n = 25) and mPDAC (n = 46) samples from the Hartwig validation dataset and performed an identical consensus clustering analysis." (PMID 36209277, 2022). "Use of the COMPASS (n = 195) and Hartwig (n = 113) validation mPDAC cohorts was an important step to mitigating sample size limitations, and our finding of molecular similarities shared between cholangiocarcinoma and KRAS wildtype mPDAC was able to be validated in this way." (PMID 36209277, 2022). "In the cholangiocarcinoma without KRAS/BRAF mutations, the transcription of AHCYL1-FGFR2 did not encode a functional protein of relevance to cancer." (PMID 35578598, 2022). "Furthermore, molecular concordances between KRAS wildtype mPDAC and cholangiocarcinoma provide impetus toward the future adoption of cholangiocarcinoma-specific treatment strategies in the clinical management of KRAS wildtype mPDAC." (PMID 36209277, 2022). "For this reason, to reliably compare cholangiocarcinoma and PDAC, two subgroups may be needed to further depict an independent role of syndecan-1, namely, KRAS-mutated and KRAS-wildtype tumors." (PMID 34206469, 2021). "In the overall cBioPortal data, KRAS was mutated in 122 of 805 cholangiocarcinoma cases (15.2%; not shown)." (PMID 34206469, 2021). "In contrast, the EGFR monoclonal antibody, cetuximab, had a modest therapeutic effect on the KRAS wild-type cholangiocarcinoma xenograft (TFK-1), but not the KRAS mutated xenograft (HuCCT1)." (PMID 29666220, 2018). "In the in vitro study, gemcitabine plus rad001 exerted a synergistic therapeutic effect on the cholangiocarcinoma cells, irrespective of the KRAS mutation status." (PMID 29666220, 2018). "We concluded that gemcitabine plus rad001 has a synergistic antiproliferative effect on cholangiocarcinoma, irrespective of the KRAS mutation status." (PMID 29666220, 2018). "In conclusion, our preclinical study shows that gemcitabine plus rad001 exerts a synergistic antitumor effect on cholangiocarcinoma irrespective of the KRAS mutation status." (PMID 29666220, 2018). "Furthermore, cholangiocarcinoma harboring FGFR2 translocation and concomitant KRAS mutation are only rarely reported." (PMID 27102149, 2016). "Collectively, the EGFR and KRAS gene status may be a potential biomarker for predicting the response to inhibitors of EGFR including vandetanib in cholangiocarcinoma." (PMID 19319137, 2009). "Additionally, the transcriptomic profile of KRAS wild-type PDAC shared similarity with cholangiocarcinoma, so therapeutic approaches used in biliary tract cancers may also be taken into consideration in KRAS wild-type PDAC." (PMID 40805153, 2025). "In the cholangiocarcinoma without KRAS mutations, the transcription of AHCYL1 was not abnormal." (PMID 35578598, 2022).
cholangiocarcinoma (continued). "Furthermore, we demonstrated, for the first time, that gemcitabine plus rad001 exerted a synergistic antitumor effect on cholangiocarcinoma, independent of the KRAS mutation status." (PMID 29666220, 2018). "To further assess the genomic similarities between cholangiocarcinoma and KRAS wildtype mPDAC, we examined the spatial distribution of CNV events across chr1 and chr8 in the POG cholangiocarcinoma samples." (PMID 36209277, 2022). "The absence of approved KRAS-targeted therapies in cholangiocarcinoma limits treatment options to gemcitabine/cisplatin chemotherapy, though emerging strategies, including MEK and SHP2 inhibitors, are under investigation." (PMID 40422514, 2025). "The putative interaction of the SOS1 inhibitor BAY-293 (Merck, Darmstadt, Germany) and the BET PROTAC ARV-771 (Arvinas, New Haven, CT, USA) has been checked using BH1467 (KRAS G12C NSCLC) and EGI-1 (KRAS G12A, cholangiocarcinoma cell line) in pilot experiments at our institution." (PMID 38023987, 2023). "Meanwhile, amplification of chr8q was not as frequent (approximately 14% of tumors) in cholangiocarcinoma compared to KRAS wildtype mPDAC." (PMID 36209277, 2022). "Lastly, our findings indicated that KRAS mutations are not exclusive to PDAC lesions, but can also occur in other pancreatobiliary lesions as well, including chronic pancreatitis, cholangiocarcinoma and IPMNs." (PMID 28125707, 2017). "These in vitro results suggest that in cholangiocarcinoma cells, upregulation of the RAS/RAF/MAPK pathway by mutant KRAS might counteract the anti-growth effect of vandetanib by EGFR inhibition." (PMID 19319137, 2009). "Taken together, these data provide evidence toward a striking molecular similarity between metastatic cholangiocarcinoma and KRAS wildtype mPDAC that is not shared with KRAS mutant mPDAC, while being observed in two orthogonal study cohorts of patient tumor samples." (PMID 36209277, 2022). "For instance, results of contemporary clinical trials investigating FGFR2 inhibition in cholangiocarcinoma, including infigratinib (NCT03773302) and futibatinib (NCT04093362), could perhaps be extrapolated to patients with FGFR2 fusion positive, KRAS wildtype PDAC." (PMID 36209277, 2022). "The absence of KRAS mutation and the presence of EGFR amplification may be potential predictive molecular marker of sensitivity to EGFR-targeted therapy in cholangiocarcinoma." (PMID 19319137, 2009). "Moreover, both the absence of KRAS mutation and the presence of EGFR amplification appear promising biomarkers for predicting the response of cholangiocarcinoma to agents that inhibit EGFR (such as vandetanib)." (PMID 19319137, 2009). "EGF, HGF/MET, VEGF, KRAS/MAPK, and IL-6/STAT pathways have been found to be deregulated in cholangiocarcinoma, but no effective therapies targeting these pathways have been developed." (PMID 26475437, 2015).
mucinous adenocarcinoma (90 papers, 2009 to 2026). An invasive adenocarcinoma composed of malignant glandular cells which contain intracytoplasmic mucin. "We present a unique case of pulmonary minimally invasive mucinous adenocarcinoma with KRAS G12D mutation in a pediatric patient who underwent VATS." (PMID 40296044, 2025). "Mucinous adenocarcinoma was more common in tumors with BRAF/NRAS mutations than in KRAS mutant or WT tumors." (PMID 41439081, 2025). "Key findings include a high frequency of KRAS mutations, a trend linking BRAF/NRAS mutations to mucinous adenocarcinoma, and a significant association between KRAS mutations and older patient age." (PMID 41439081, 2025). "A 10­-day-old male neonate presented with type 2 CPAM in the left lower lobe complicated by multifocal mucinous adenocarcinoma harboring the KRAS G12D mutation." (PMID 40296044, 2025). "Mucinous adenocarcinoma occurred more than twice as frequently in BRAF/NRAS-mutated tumors as in KRAS-mutated tumors, and more than four times as frequently as in WT tumors." (PMID 41439081, 2025). "Based on a comparison of homology, mucinous adenocarcinoma in humans most frequently carries mutations in the KRAS gene region that is homologous to the PasI susceptibility locus in tumor-prone mice such as CD-1." (PMID 38440945, 2024). "Further studies are required to identify specific gene alterations other than KRAS mutations in colloid adenocarcinoma." (PMID 39307027, 2024). "Molecular analysis of the mucinous cells in our study revealed KRAS G12D mutations, which are commonly observed in de novo mucinous adenocarcinomas in adults." (PMID 39229431, 2024). "For histological type, frequency of KRAS mutation was higher in poorly cohesive carcinoma (75%, n = 3/4), than in other histological types (58.8% in mucinous adenocarcinoma, 51.9% in adenocarcinoma NOS)." (PMID 37277698, 2023). "KRAS mutations were more prevalent in mucinous carcinoma than in adenocarcinoma or signet-ring cell carcinoma (72.0% vs 39.0% vs 57.1%, P = .006)." (PMID 36862900, 2023). "In this study, KRAS mutation prevalence, subtypes, rates of occurrence in treatment-resistant invasive mucinous adenocarcinomas (IMAs), and novel drug delivery options are reviewed." (PMID 36980522, 2023). "The three other patients with lung metastases only were diagnosed with mucinous adenocarcinoma and KRAS mutations were detected only in tissue samples among these patients." (PMID 37751775, 2023). "Other less common cancers that have high rates of KRAS mutations include appendiceal mucinous adenocarcinomas with rates of 60–80% and ovarian mucinous carcinomas with rates of 64%." (PMID 36980522, 2023). "KRAS mutation was identified in codon 12 in eight mucinous carcinomas and codon 13 in one mucinous carcinoma." (PMID 37110218, 2023). "This review examines KRAS mutation prevalence, subtypes, and rates in treatment-resistant invasive mucinous adenocarcinomas (IMAs) and novel drug delivery options." (PMID 36980522, 2023). "Mucinous carcinoma with KRAS mutations are reported in cystadenomas, borderline tumors, and mucinous carcinomas." (PMID 36675280, 2023). "KRAS mutations have been linked to the clinicopathological, immunohistochemical and molecular characteristics of pulmonary invasive mucinous adenocarcinoma." (PMID 35545933, 2022). "In contrast to the positive correlation between mucinous carcinoma and the KRAS mutation, our results suggest that SC was associated negatively with the KRAS mutation, suggesting the distinct clonal origins of SC and mucinous carcinomas." (PMID 35888555, 2022).
mucinous adenocarcinoma (continued). "For example, usually, low-grade serous carcinoma has ERBB2, BRAF and KRAS mutations, mucinous carcinoma has KRAS mutation, clear cell carcinoma has ARIDIA and PIK3CA mutations, and endometrioid cell carcinoma has CTNNB1, PTEN and PIK3CA mutations." (PMID 34041032, 2021). "Factors associated with a high KRAS exon 4 mutation rate included advanced age, tumor type histology, and mucinous carcinoma." (PMID 34335949, 2021). "KRAS mutations are more prevalent in tubular IPMC than in colloid carcinomas (80–90% versus 30–50%)." (PMID 34201897, 2021). "GNAS only mutated tumors are almost all of the intestinal subtype and GNAS mutated colloid carcinomas harbor way less KRAS mutations than GNAS mutated tubular lesions (40–50% versus 80%)." (PMID 34201897, 2021). "Our results showed that KRAS was the main mutated gene in appendiceal mucinous adenocarcinoma, especially in exon 2 (4/9 cases), followed by RNF43 (3/9)." (PMID 33712927, 2021). "KRAS mutations are common in mucinous carcinomas and have been reported to develop according to the adenocarcinoma sequence over a relatively long period of time." (PMID 34885229, 2021). "In that study, the presence of KRAS mutations suggested that the sarcomatous component represented a dedifferentiated form of mucinous adenocarcinoma mostly likely." (PMID 32290854, 2020). "Patient is a 43-year-old woman with KRAS mutated (G12V) metastatic mucinous adenocarcinoma who was first diagnosed at age 36 with widespread peritoneal disease." (PMID 30923702, 2019). "A common genetic defect of ovarian mucinous tumors is represented by KRAS mutations, observed in 46–55% of mucinous cystadenomas, in 63% to 73% of borderline tumors and in 75–85% of mucinous carcinomas." (PMID 29389895, 2018). "Mucinous adenocarcinoma is strongly correlated with KRAS (Kirsten rat sarcoma viral oncogene homolog) mutations." (PMID 28819306, 2017). "The strongest correlation between a histological subtype and a set of molecular and biologic features is that of invasive mucinous adenocarcinomas, which typically have KRAS mutations and lack EGFR mutations." (PMID 29065153, 2017). "The current patient had a series of unfavorable prognostic factors besides having a mucinous adenocarcinoma: rapidly growing locally advanced tumor, thrombocytosis and KRAS mutation." (PMID 26555668, 2015). "KRAS mutation is associated with mucinous differentiation, because these mutations also accumulate in mucinous carcinomas of other organs." (PMID 24936796, 2014). "KRAS gene was wild type in 18 cases, whereas one mucinous carcinoma harboured a point mutation at codon 12 (G12R)." (PMID 24454858, 2014). "It is likely that KRAS mutation is associated with mucinous differentiation as these mutations also accumulate in mucinous carcinomas obtained from other organs." (PMID 19358724, 2009). "A previous study that examined the expression of HNF4α and mucin profiles in lung mucinous adenocarcinomas reported that HNF4α induced the expression of MUC3 in KRAS-mutated mucinous adenocarcinomas, which is a poor prognostic factor for mucinous adenocarcinomas of the breast and appendix." (PMID 38710944, 2025). "Therefore, KRAS mutations play an essential role in the development of pulmonary mucinous adenocarcinomas in pediatric patients." (PMID 40296044, 2025). "In addition, KRAS-driven but NKX2.1-deficient lung tumors display a mucinous adenocarcinoma pathology and other transcriptional features of a pulmonary-to-gastric lineage switch." (PMID 39213022, 2024). "MSI-H in CRC is associated with pathological features such as mucinous carcinoma, proximal colon, poorly differentiation, lymphatic invasion, tumor staging, tumor size, KRAS mutation, and BRAFV600E mutation; some results of our study are consistent with these findings." (PMID 37182124, 2023). "In our study, KRAS exon 2 mutations were present in all 7 mucinous adenocarcinomas." (PMID 37737217, 2023).